TCF7L2 (transcription factor 7 like 2)
Diseases named in the same sentence as TCF7L2 in open-access papers (continued):
Sharing a sentence is not in itself a finding about the gene and the disease.
type 2 diabetes (continued). "TCF7L2 SNPs are strongly associated with various aspects of type 2 diabetes, including insulin resistance, impaired insulin secretion, altered insulin processing, diminished suppression of glucagon by glucose, and increased fasting hepatic glucose release." (PMID 33828529, 2021). "It has been demonstrated that transcription factor 7-like 2 (TCF7L2)-rs7903146 polymorphism is associated with increased risk of type 2 diabetes and the response of insulin." (PMID 33126534, 2020). "The SNP rs7903146 is one of the most studied polymorphisms associated with type 2 diabetes within TCF7L2 gene." (PMID 32961860, 2020). "Genetics studies have reported a positive association between type 2 diabetes predisposing alleles within TCF7L2 and cancer including colorectal, breast hepatocellular and aggressive prostate cancer." (PMID 32705315, 2020). "The association between type 2 diabetes risk alleles in TCF7L2 and higher risk of colorectal cancer has been replicated in several studies." (PMID 32705315, 2020). "Common genetic variants of TCF7L2 have been reproducibly associated with the risk for type 2 diabetes (T2DM) in multiple genome-wide association studies." (PMID 33081636, 2020). "In type 2 diabetes, the most strongly associated SNP lies within the TCF7L2 gene, with the rs7903146 T allele in intron 3 widely implicated as the causal variant." (PMID 32797243, 2020). "Type 2 diabetes was associated with TCF7L2 (RRpooled 1.46, 95% CI, 1.35-1.59) and FTO (RRpooled 1.15, 95% CI 1.06-1.26) but not with HLA (RRpooled 0.94, 95% CI, 0.86-1.02)." (PMID 32835373, 2020). "This is the situation for a variant in the FTO gene that is most strongly associated with obesity which actually regulates IRX3, and a variant in TCF7L2 most strongly associated with type 2 diabetes that regulates ACSL5." (PMID 32797243, 2020). "It belongs to the same family as the well-known type 2 diabetes susceptibility gene transcription factor 7 like 2 (TCF7L2) found in multiple GWAS studies." (PMID 31959221, 2020). "SNPs in TCF7L2 were previously reported to be strongly associated with type-2 diabetes and this gene plays a role in the pancreatic insulin secretory response to incretins." (PMID 33303027, 2020). "Another gene named Transcription factor 7-like-2 (TCF7L2) and implicated in type 2 diabetes mellitus interacts with the Mediterranean diet in the reduction of stroke risk." (PMID 33228237, 2020). "LADA has also been linked to genes associated with type 2 diabetes, for example, risk variants of the transcription factor 7-like 2 (TCF7L2) gene and in one study, with the fat mass and obesity-associated (FTO) gene." (PMID 32835373, 2020). "A recent comprehensive meta-analysis found type 2 diabetes risk alleles at eight variants in TCF7L2 were associated with increased risk of breast, colorectal and lung cancer and glioma." (PMID 32705315, 2020). "Fine-mapping of the TCF7L2 locus suggested one type 2 diabetes association signal shared between Europeans and Africans (indexed by rs7903146) and a distinct African-specific signal (indexed by rs17746147)." (PMID 31049640, 2019). "The most significantly associated variants mapped to the widely replicated type 2 diabetes risk locus near TCF7L2 (p = 5.3 × 10−13)." (PMID 31049640, 2019). "The Wnt signaling pathway regulator TCF7L2 is associated with an increased risk of type 2 diabetes and negative regulators of hepatic gluconeogenesis." (PMID 30732658, 2019). "Tcf7l2 mediates Wnt/β-Catenin signalling during development and is implicated in cancer and type-2 diabetes." (PMID 31829936, 2019). "Carriers of the TCF7L2 risk allele have a significantly increased risk to develop type 2 diabetes mellitus." (PMID 30846969, 2019). "The transcription factor 7-like 2 (TCF7L2) polymorphism rs7903146 is known to be tightly associated with an elevated risk for type 2 diabetes, whereas the molecular mechanisms remain elusive." (PMID 31492908, 2019).
type 2 diabetes (continued). "Genetic variants of TCF7L2 correlate with susceptibility to type 2 diabetes and Crohn’s disease and the aberrant expression of TCF7L2 has also been linked to the risk of cancer." (PMID 31089877, 2019). "Among them, TCF7L2 has been recognized as a type 2 diabetes (T2D) risk gene, revealed by reproducible genome-wide association studies (GWASs)." (PMID 31589598, 2019). "Some previous studies have reported increased chromatin accessibility and episomal enhancer activity for the T allele SNP and higher TCF7L2 expression was found in carriers of the TT genotype with type 2 diabetes." (PMID 31161346, 2019). "For example, some mutations in genes involved in a higher risk for type 2 diabetes (e.g. TCF7L2) are also associated with a higher and earlier CFRD prevalence." (PMID 30894563, 2019). "Particularly, TCF7L2 is known as a major type 2 diabetes susceptibility gene, which is also linked to diabetic coronary atherosclerosis." (PMID 31492908, 2019). "The most significant signal for type 2 diabetes association, rs7903146 at TCF7L2 (p = 5.3 × 10−13), has been widely reported in other ethnic groups." (PMID 31049640, 2019). "One of the strongest association signals for type 2 diabetes is the rs7903146 T allele SNP in the TCF7L2 gene, and researchers have tried hard to understand the molecular mechanism behind this association." (PMID 31161346, 2019). "Rs7903146 in TCF7L2 gene was reported associated with type 2 diabetes in several different populations, which agrees with our current results (P = 2.3E-12)." (PMID 30704471, 2019). "Variants in several genes show strong association with type 2 diabetes risk, including those in TCF7L2, SLC30A8 and MTNR1B." (PMID 31161346, 2019). "Recently, it was shown that CRISPR-mediated deletion of the region harbouring the type 2 diabetes risk SNP rs7903146 leads to a decrease in TCF7L2 mRNA levels, while targeting it with a CRISPR transcriptional activator had the opposite effect." (PMID 31161346, 2019). "Both rs11196205 [OMIM:125853] and rs122555372 [OMIM:125853] are variants located in TCF7L2 gene, that has been widely studied as a marker for Type 2 Diabetes Mellitus." (PMID 31604968, 2019). "The maternal birth weight-associated variants at MTNR1B, GCK and TCF7L2 loci are known to be associated with fasting glucose and Type 2 diabetes susceptibility, with the glucose-raising allele associated with higher offspring birth weight." (PMID 29309628, 2018). "Among these risk loci, TCF7L2 seems to be one of the strongest risk loci [P = 2.1 × 10-9] for type 2 diabetes." (PMID 30065654, 2018). "We then used structural equation models to simultaneously model the genetic association on changes in body mass index across the life course and estimate the odds of type 2 diabetes per TCF7L2 risk allele." (PMID 30305909, 2018). "Genome-wide association studies have implicated the transcription factor 7-like 2 (TCF7L2) gene in type 2 diabetes risk, and more recently, in decreased body mass index." (PMID 30305909, 2018). "Since 2006, intensive genome-wide association studies (GWAS) have revealed that TCF7L2 is among the type 2 diabetes risk genes, while the expression of dominant negative TCF7L2 (TCF7L2DN) was shown to stimulate adipogenesis." (PMID 28102847, 2017). "SNP rs7903146 in the Wnt pathway’s TCF7L2 gene is the variant most significantly associated with type 2 diabetes to date, with associations observed across diverse populations." (PMID 28253288, 2017). "Genetic variants comprising the optimal models for PSMD2 and TCF7L2: associations with risk of type 2 diabetes in the BWHS." (PMID 28253288, 2017). "In 2006, researchers of the deCODE project based in Iceland identified TCF7L2 gene polymorphisms in a binding region of chromosome 10 that were strongly associated with the risk of type 2 diabetes." (PMID 28420445, 2017). "Genetic variants of TCF7L2 showed the strongest association with type 2 diabetes/gestational diabetes mellitus to date." (PMID 28993636, 2017).
type 2 diabetes (continued). "Most notable is SNP rs7903146 in the TCF7L2 gene, the variant most significantly associated with type 2 diabetes to date." (PMID 28253288, 2017). "Transcription factor TCF7L2, involved in Wnt signaling, has been reported to play an important role and to be one of the risk factors in type 2 diabetes." (PMID 28218651, 2017). "TCF7L2 is known as the ‘top’ diabetes gene, and the genotype increasing the risk for type 2 diabetes is also associated with increased TCF7L2 expression in human islets." (PMID 27796421, 2017). "This is consistent with the finding that SCZ patients are at increased risk of comorbidities such as type 2 diabetes, and that TCF7L2 is associated with type 2 diabetes." (PMID 28404897, 2017). "We evaluated 69 genes involved in the Wnt pathway, including TCF7L2, for associations with type 2 diabetes in 2632 African American cases and 2596 controls from the Black Women’s Health Study." (PMID 28253288, 2017). "Consistent with that idea, genetic variants of TCF7L2 are associated with the risk of type 2 diabetes and gestational diabetes mellitus." (PMID 28404897, 2017). "The most significantly associated variant in the TCF7L2 region was the GWAS index SNP rs7903146 (p = 1.0 x 10−5), which was associated with a ~20% increased risk of type 2 diabetes (OR 1.21, 95% CI 1.11, 1.32)." (PMID 28253288, 2017). "SNPs in the TCF7L2 gene have previously been associated with an increased risk of type 2 diabetes in genome-wide association studies." (PMID 28343277, 2017). "Several genome wide association studies indicate that several components of the Wnt signaling pathway including TCF7L2, the nuclear partner of β-catenin, are genetic determinant of type 2 diabetes (T2D) risk in humans." (PMID 26974334, 2016). "The TCF7L2 rs7903146 variant interacted with quintiles of fiber intake on type 2 diabetes incidence (Pinteraction = 0.034)." (PMID 27551309, 2016). "We identified a possible interaction between TCF7L2 and coffee, with carriers of the type 2 diabetes risk-conferring T allele benefiting more from coffee consumption than non-carriers." (PMID 27623947, 2016). "Our large-scale case-cohort study provides some evidence for a possible interaction of TCF7L2 variants and an incretin-specific genetic risk score with coffee consumption in relation to the risk of type 2 diabetes." (PMID 27623947, 2016). "Of these, the transcription factor 7-like 2 gene (TCF7L2) variant rs7903146 shows the strongest association with type 2 diabetes." (PMID 27551309, 2016). "TCF7L2 is a member of the high mobility group DNA binding protein family of transcription factors which has been implicated in type 2 diabetes risk." (PMID 27454520, 2016). "Variants in TCF7L2 gene have been reported to affect insulin secretion and body mass index and to promote type II diabetes." (PMID 27936208, 2016). "Our analyses show some evidence for a possible TCF7L2–coffee interaction, as well as an overall interaction of an incretin-specific genetic risk score with coffee on type 2 diabetes risk." (PMID 27623947, 2016). "The rs7903146 polymorphism is located in an intronic region of TCF7L2 and known to be related toan increased type 2 diabetes risk." (PMID 27738320, 2016). "TCF7L2 is a central transcription factor in the canonical wingless-type MMTV integration site (WNT) signaling pathway, and genetic variants in TCF7L2 have been found to interact with dietary fiber intake on type 2 diabetes risk." (PMID 27551309, 2016). "The transcription factor-7-like-2 (TCF7L2) gene has been consistently associated with type 2 diabetes mellitus (T2D) in different ethnic groups, and with fasting glucose levels." (PMID 26914832, 2016). "Our population-based case–cohort study provides evidence for the possible interaction of a TCF7L2 variant and an incretin-specific genetic risk score with coffee consumption affecting the risk of type 2 diabetes." (PMID 27623947, 2016).
type 2 diabetes (continued). "The possible relevance of these findings for the action of TCF7L2 polymorphisms associated with Type 2 diabetes in man is discussed." (PMID 25355422, 2015). "Human genetics studies have revealed that common variants of the TCF7L2 gene are strongly associated with type 2 diabetes mellitus." (PMID 25794287, 2015). "The minor allele (T) of the TCF7L2 rs7903146 variant (C/T), located in intron 4 of TCF7L2, has been associated with increased risk for type 2 diabetes." (PMID 26576435, 2015). "Non-coding variation within TCF7L2 remains the strongest genetic determinant of type 2 diabetes risk in humans." (PMID 25398947, 2015). "Polymorphisms of TCF7L2 have been identified as one of the most important genetic predictors of type 2 diabetes in genome-wide association studies." (PMID 26576435, 2015). "TCF7L2 has been associated with fasting plasma insulin, with glucose levels in type 2 diabetes patients to some extent with BMI, and with adipogenesis." (PMID 26608632, 2015). "Our meta-analysis indicated the association between TCF7L2 rs7903146 polymorphism and low plasma triglyceride (TG) level in subjects with type 2 diabetes." (PMID 26576435, 2015). "It is well known that transcription factor TCF7L2 is closely associated with type 2 diabetes and plays an important role in glucose metabolism." (PMID 25794287, 2015). "This study, with a caution on sample size showed an association between the rs12255372 (G/T) polymorphism of the TCF7L2 gene and type 2 Diabetes in a Cameroonian population." (PMID 25995831, 2015). "Variants of the transcription factor 7-like 2 gene (TCF7L2) have been associated with type 2 diabetes and cardiovascular disease in different populations." (PMID 24574000, 2014). "Some SNPs have been consistently replicated across multiple ancestral populations - for example, the primary TCF7L2 variant for type 2 diabetes (T2D) and the variant in the 9p.21 region for coronary artery disease." (PMID 25473427, 2014). "The transcription factor 7-like 2 (TCF7L2) gene is the most significant genetic risk factor for type 2 diabetes (T2D)." (PMID 25491720, 2014). "More recently, several genome-wide association studies (GWAS) independently confirmed the strong associations of SNP rs7903146 in the TCF7L2 locus with type 2 diabetes." (PMID 25309595, 2014). "Individuals carrying variants of the transcription factor 7-like 2 gene (TCF7L2) are at increased risk for type 2 diabetes." (PMID 24906949, 2014). "TCF7L2 is the susceptibility gene for Type 2 diabetes (T2D) with the largest effect on disease risk that has been discovered to date." (PMID 24914535, 2014). "So far TCF7L2 is the most significant and reproducible susceptibility gene for type 2 diabetes in various ethnic groups." (PMID 24574000, 2014). "Recently, single-nucleotide polymorphisms (SNPs) of a gene encoding transcription factor 7-like 2 were shown to have the strongest known genetic risk factor for type 2 diabetes among all diabetes-associated gene SNPs." (PMID 24906949, 2014). "Single nucleotide polymorphisms (SNPs) of gene encoding transcription factor 7-like 2 (TCF7L2) were shown to have the strongest association with type 2 diabetes among all diabetes associated gene SNPs." (PMID 23509454, 2013). "The 7th ranked factor Tcf7l2 (activity score of 1.38) was linked to type 2 diabetes risk in previous studies using SNP data, but the mechanism for its involvement was unclear." (PMID 24238150, 2013). "In multivariate analysis adjusting for age, gender, BMI ≥25.0 kg/m2 and hypertension status, TCF7L2 (T) was associated with increased odds of type 2 diabetes (aOR, 1.39; Bonferroni-corrected p = 0.056)." (PMID 24059590, 2013). "Transcription factor 7-like 2 (TCF7L2) has been strongly linked to type 2 diabetes(T2D) susceptibility, with an elevated genetic predisposition accounting for 20% ofT2D cases." (PMID 23617586, 2013).
type 2 diabetes (continued). "The following studies further confirmed the association between TCF7L2 rs7903146 variant and type 2 diabetes." (PMID 23951231, 2013). "TCF7L2 gene variant rs12255372 has been reported to be associated with risk of Type 2 diabetes in different populations." (PMID 23516639, 2013). "GoDARTS was the first pharmacogenetic study to address the relationship between the TCF7L2 rs12255372 (G/T) and rs7903146 (C/T) gene variants and response to sulphonylurea therapy in type 2 diabetic patients." (PMID 24324494, 2013). "Recently, variants of transcription factor 7-like 2 (TCF7L2), a component of Wnt/β-catenin signaling, have been shown to be involved in β-cell dysfunction and the pathogenesis of type 2 diabetes." (PMID 23874448, 2013). "We aimed to replicate the association of the rs290487 (IVS3C/T) and rs7903146 (IVS3C/T) polymorphisms of transcription factor 7-like 2 (TCF7L2) and type 2 diabetes mellitus (T2DM) in Han Chinese people in Henan province, China." (PMID 23536853, 2013). "In urban Ghana, the frequency of the TCF7L2 rs7903146 (T) allele is comparable to the one in Caucasians; the association with type 2 diabetes is slightly weaker." (PMID 24059590, 2013). "Associations between transcription factor 7-like 2 (TCF7L2) polymorphisms and type 2 diabetes mellitus (T2DM) have been evaluated extensively in multiple ethnic groups." (PMID 23311683, 2013). "Polymorphisms in the transcription factor 7-like 2 (TCF7L2) gene have been shown to display a powerful association with type 2 diabetes." (PMID 24205231, 2013). "We note that TCF7L2 harbors the common allele most strongly associated with increased risk of type 2 diabetes." (PMID 23844908, 2013). "While the genetic basis of type 2 diabetes mellitus in Indians is the same as in Caucasians (that is, a strong association of TCF7L2 variants with type 2 diabetes), there are other factors that make this population a unique cohort." (PMID 24451035, 2013). "So far, most of the work in African populations, mainly African Americans, has focused on the TCF7L2 variant, revealing MAFs of around 0.34 and ORs for type 2 diabetes of 1.37." (PMID 24059590, 2013). "Variation in the TCF7L2 locus has previously been associated with Type 2 diabetes in a number of GWAS." (PMID 23544013, 2013). "Recent linkage studies and GWAS have identified >40 genes that increase the risk of type 2 diabetes with the most important diabetes susceptibility gene identified as transcription factor 7-like 2 (tcf7l2), which increases diabetes risk 1.7-fold." (PMID 23542897, 2013). "Another target, Tcf7l2, is also involved in insulin secretion and genetic variation in this gene is a risk factor for type 2 diabetes." (PMID 24109547, 2013). "Rs7903146 variant of TCF7L2 gene was firstly identified as one susceptibility marker of type 2 diabetes by genome-wide association study." (PMID 23951231, 2013). "A total of 51 patients were homozygous for wild type C-allele (CC genotype), 41 patients were heterozygous (CT genotype), and 9 patients were homozygous for the type 2 diabetes associated T-allele (TT genotype) of TCF7L2 rs7903146." (PMID 23509454, 2013). "Among more than 50 gene variants associated with T2D, the variants in transcription factor 7-like 2 (TCF7L2) gene are the strongest predictors of increased risk of developing type 2 diabetes, a 40% increased risk per allele." (PMID 24324494, 2013). "A variant in TCF7L2 associated with type 2 diabetes (the T allele at rs7903146) was associated with diabetes in CF in the family study (p = 0.004) and in the case–control study (p = 0.02; combined p = 0.0002)." (PMID 23050589, 2012). "Further studies are needed to answer these questions and to understand the mechanisms by which the TCF7L2 risk variant increases the risk of type 2 diabetes." (PMID 22782288, 2012).